BRCA1 (BRCA1 DNA repair associated)
Diseases named in the same sentence as BRCA1 in open-access papers (continued):
Sharing a sentence is not in itself a finding about the gene and the disease.
gastric cancer (continued). "In our previous studies, high levels of BRCA1 mRNA were negatively associated with cisplatin sensitivity but positively associated with docetaxel sensitivity in gastric cancer patients." (PMID 23326344, 2013). "Importantly, there has been a steady accumulation of clinical data suggesting that BRCA2, and to a slightly lesser extent BRCA1, carriers also have an increased risk of gastric cancer (GC)." (PMID 41256354, 2025). "Another study confirmed a significant association between the rs799917 CT SNP and the risk of gastric cancer (OR = 1.81, p = 0.001) and suggested that rs799917C interferes with the interaction between BRCA1 mRNA and miR-638, resulting in reduced BRCA1 expression." (PMID 40361383, 2025). "Several studies have already observed association between BRCA1 expression and gastric cancer." (PMID 37568604, 2023). "Currently, it is remains uncertain whether BRCA1/2 carriers are also at an increased risk for gastric cancer." (PMID 36497436, 2022). "BRCA1 gene polymorphisms have also been associated with susceptibility to gastric cancer." (PMID 33987081, 2021). "The loss of BRCA1 expression may serve as a predictive factor for the progression of gastric cancer." (PMID 27403158, 2016). "The BRCA1 variant allele (T) is associated with better overall survival and longer progression-free survival compared to the reference allele in patients with advanced gastric cancer treated with taxanes and cisplatin." (PMID 26180747, 2015). "Our current study showed that BRCA1 mRNA was associated with gastric cancer differentiation." (PMID 25646628, 2015). "Lost expression of BRCA1 protein was associated with poor survival rate of gastric cancer patients." (PMID 25646628, 2015). "In addition to BC, BRCA1 is a well-established OC susceptibility gene, with a cumulative risk to age 80 years of 44% for female BRCA1 PV carriers; moreover, BRCA1 PVs were recently associated with a twofold increased risk of pancreatic and stomach cancers in both sexes." (PMID 38339330, 2024). "There is mounting evidence that BRCA1/2 PV carriers also have an elevated risk of gastric cancer (GC)." (PMID 36497436, 2022). "Other reports are mainly indirect and family-based studies, in which a risk of gastric cancer was analyzed on the basis of the observed and expected number or incidence of GC in BRCA1/2 mutation carriers or their relatives." (PMID 26779294, 2016). "However, some research has suggested that while there are evident connections between breast and ovarian, and prostate, pancreatic or stomach cancers, it is possible that such links may be due to factors other than possessing a mutated BRCA1/2 gene." (PMID 26236408, 2015). "Recent evidence suggests that carriers of a pathogenic germline variant (PGV) in BRCA1 or BRCA2 may have an increased risk of gastric cancer (GC)." (PMID 42286806, 2026). "Ultimately, a better understanding of gastric carcinogenesis in BRCA1 and BRCA2 carriers will have important implications for gastric cancer risk management amongst this high-risk cohort." (PMID 41256354, 2025). "For female BRCA1 GPV carriers, a significantly increased risk was found for pancreatic and stomach cancer." (PMID 40427184, 2025). "In one case-control study of 63,828 patients with 14 common cancer types and 37,086 controls in Japan, pathogenic variants in BRCA1 were associated with biliary tract cancer, in BRCA2 with esophageal cancer, and in BRCA1/2 with gastric cancer." (PMID 39996890, 2025). "This signal for FA genes was mostly driven by BRCA1/2; when we removed BRCA1/2 and reperformed the analysis, we still observed associations of germline RDV load in FA genes and TMB for stomach cancer." (PMID 36707626, 2023).
gastric cancer (continued). "The most common cancers in male relatives of BRCA1 carriers were lung (7.2%), esophageal (6.2%), and gastric cancers (4.8%), followed by liver cancer and lymphoma (2.4% each)." (PMID 36861435, 2023). "Gastric cancer patients with BRCA1-negative status benefited from platinum-based adjuvant chemotherapy (p = 0.024) in comparison with patients with BRCA1-positive expression." (PMID 37568604, 2023). "Studies have shown that high cytoplasmic expression of BRCA1 has a higher overall survival (OS) rate in gastric cancer, whereas nuclear expression of BRCA1 usually indicates adverse outcomes." (PMID 36035159, 2022). "In this case-control study of 63 828 patients with 14 common cancer types and 37 086 controls, pathogenic variants in BRCA1 were associated with biliary tract cancer, in BRCA2 with esophageal cancer, and in BRCA1/2 with gastric cancer." (PMID 35420638, 2022). "In this review, we discuss emerging evidence that BRCA2 PV carriers, and likely also BRCA1 PV carriers, are also at increased risk for gastric cancer (GC), highlighting that GC may be part of the BRCA1/2 cancer risk spectrum." (PMID 36497436, 2022). "In a large cohort of 367 patients with sporadic gastric cancer BRCA1 and BRCA2 mRNA levels were investigated by IHC, ISH and RT-qPCR." (PMID 34707985, 2021). "Most (85.7%) of the BRCA1/2 carriers had gastric or GEJ tumors, in line with prior studies that suggested the potential role of BRCA in gastric cancer susceptibility." (PMID 34251444, 2021). "Different gastric cancer cell lines were examined regarding their protein levels of BRCA1, BRCA2 and c‐MET using Western blot analysis." (PMID 32686903, 2020). "This leads to a reduction of gastric cancer cells viability, especially after knockdown of BRCA1/2 through apoptosis and induction of γ‐Η2ΑΧ." (PMID 32686903, 2020). "There are several studies which investigated the role of BRCA1/2 gene in gastric cancer in different populations." (PMID 26779294, 2016). "In 150 gastric cancer patients, mRNA levels of BRCA1 and TS were assessed in plasma and paired tumor tissue." (PMID 25496700, 2014). "We also examined the expressions of FANCJ and BRCA1 in other gastric cancer cell lines, such as MKN1, TMK1, and MKN45/F2R cells." (PMID 22968820, 2013). "BRCA1 expression levels and polymorphic status has been shown to correlate with sensitivity to chemotherapeutics in gastric cancer." (PMID 21781349, 2011). "The absence of mutations in other DDR-related genes such as ataxia-telangiectasia mutated (ATM), BRCA1, mutL homolog 3 (hMLH3), and Nijmegen breakage syndrome protein 1 (NBS1) suggested a selective vulnerability of the ATR-CHK1 axis in MSI-high gastric cancers." (PMID 40869030, 2025). "We identified BRCA1 methylation in 3% of the copy-number high subtype of endometrial cancer, and as a rare event in six other cancer types, including lung squamous cell, pancreatic, bladder and stomach cancer." (PMID 39055334, 2024). "In the TCGA gastric cancer WES dataset, we identified two cases with a pathogenic BRCA2 mutation accompanied by LOH, one BRCA2 case where both alleles had pathogenic mutations, and two cases with pathogenic BRCA1 mutation accompanied by LOH." (PMID 38589664, 2024).
gastric cancer (continued). "Similar to the TCGA gastric cancer cohort, there were an additional 68 of 179 cases (40%) without a BRCA1/2 or other HR gene mutation that also had an HRD score larger than the threshold." (PMID 38589664, 2024). "In the TCGA WES gastric cancer cohort, three BRCA2 deficient, four PALB2 deficient, two BRCA1 deficient and three BRCA1 promoter methylated cases all had an HRD score ≥42 (p < 1 × 10-5, Fisher exact test), which is the threshold for HR deficiency previously defined for ovarian cancer." (PMID 38589664, 2024). "The results showed that RAD51D was not a risk factor for gastric cancer, but other BRCA1, BRCA2, and ATM genes from the homologous recombination pathway are risk factors for gastric cancer." (PMID 39206620, 2024). "Consequently, 315 pathogenic BRCA variants were identified, and an odds ratio of greater than 4.0 were found for biliary tract cancer in BRCA1, esophageal cancer in BRCA2, and gastric cancer in BRCA1 and BRCA23." (PMID 37113971, 2023). "The associations between BRCA1/2 carriers and other cancers, such as colorectal and gastric cancers, have not been established, thus warrant further investigation." (PMID 36861435, 2023). "Lastly, we present gastric cancer risk management considerations for BRCA1/2 carriers as currently no such recommendations exist." (PMID 36497436, 2022). "However, in gastric cancer, mutation rates in HRD genes (BRCA1 and BRCA2) are low, and individual PARP inhibitors have limited efficacy." (PMID 35480096, 2022). "Our study found that PARP1 inhibitors in combination with OXA have a powerful anti-tumor effect in gastric cancer patients without BRCA1 mutations." (PMID 34497808, 2021). "Interestingly, the location of BRCA1 in gastric cancer cells was reported to be different, and different expression levels were observed." (PMID 33987081, 2021). "BRCA2 mutation increased gastric cancer incidence (RR 2.15 [1.98–2.33]), whereas BRCA1 did not increase gastric cancer incidence." (PMID 34577828, 2021). "Our study found that PARP1 inhibitors in combination with oxaliplatin have a powerful anti-tumor effect in gastric cancer patients without BRCA1 mutations." (PMID 34497808, 2021). "BRCA1/2 are tumor suppressors involved in pathways important for regulating DNA damage, and BRCA2 mutations were found to be associated with familial aggregations of not only breast but also of stomach cancers." (PMID 30866995, 2019). "BRCA1 was previously suggested as a good prognostic factor for gastric cancer." (PMID 27403158, 2016). "In conclusion, current data on the Polish population lead to the conclusion that BRCA1 founder mutations do not contribute to increased risk of gastric cancer." (PMID 26779294, 2016). "Test results indicate a mutation in a gene responsible for stomach cancer (but no BRCA1 or BRCA2 mutation)." (PMID 27586379, 2016). "In conclusion, plasma mRNA expression levels of BRCA1 and TS could mirror those in the tumor and may have a promising role as potential predictive biomarkers for docetaxel and peretrexed in gastric cancer." (PMID 25496700, 2014). "For example, gastric cancer patients with low levels of plasma TS mRNA can be treated with pemetrexed-based chemotherapy, while those with high levels of plasma BRCA1 could benefit from treatment with docetaxel." (PMID 25496700, 2014). "We examined gene expression of APTX, BRCA1, ERCC1, ISG15, Topo1 and methylation of SULF2 in formalin-fixed paraffin-embedded gastric cancer tissues from 175 patients and evaluated the association between gene expression levels or methylation status and in vitro sensitivity to irinotecan." (PMID 23517622, 2013). "A differential modulating effect for BRCA1 mRNA expression was also observed in tumor cells isolated from malignant effusions of non-small-cell lung cancer and gastric cancer patients, whose BRCA1 mRNA levels correlated negatively with cisplatin sensitivity and positively with docetaxel sensitivity." (PMID 20209131, 2010).
gastric cancer (continued). "In addition, BRCA1 mRNA expression was negatively correlated with cisplatin sensitivity in peritoneal effusions of gastric cancer patients, while ERCC1 was correlated with cisplatin sensitivity only in specimens of untreated gastric patients." (PMID 18402708, 2008). "This included KE39, a gastric carcinoma cell line that is homozygous for a missense mutation in BRCA1 (Y1853C) but was not originally labeled as BRCA1/2-deficient because this mutation was not deemed damaging by our initial criteria (see “Materials and Methods”)." (PMID 39485057, 2024). "Interestingly, they were found in intestinal gastric cancer samples, despite the lack of BRCA1/2 mutations." (PMID 37568604, 2023). "Both, BRCA1 and BRCA2 variants were associated with higher HRD scores in BRCA (FDR < 1.3 × 10−42) and OV (FDR < 5.0 × 10−12), BRCA2 (but not BRCA1) variants were also associated with higher HRD of PAAD (FDR = 1.3 × 10−17) and stomach cancer (STAD) (FDR = 6.7 × 10−17)." (PMID 34572800, 2021). "In the case of the CRC and the stomach carcinoma, the hypermutation detected was due to the presence of microsatellite instability (MSI) (MMR deficiency signatures’ contribution: 77%), and to the presence of BRCA2 p.Pro1088Leufs*16 (BRCA1/2 signature contribution: 52%), respectively." (PMID 32792570, 2020). "The majority of published analyses on the correlation between BRCA1 and BRCA2 mutations and GC are indirect and based on the observation of GC incidence in families with detected mutation, but do not show the prevalence of BRCA1/2 mutations in patients with diagnosed gastric cancer." (PMID 26779294, 2016). "The men with BRCA1 mutations were not at an increased risk of gastric cancer." (PMID 26779294, 2016). "Indeed, we have also observed that knock-down of BRCA1 or BRCA2 could sensitize Olaparib effect in MKN28 gastric cancer cells." (PMID 26540566, 2015). "Since cancers with defective homology directed double-strand break repair due to BRCA1 or BRCA2 mutations are particularly sensitive to platinum therapy and PARP inhibitors, it is conceivable that this subset of gastric cancers might also benefit from their usage." (PMID 26511885, 2015). "Analysis of the selected literature suggests that mutation of the BRCA2 gene, rather than BRCA1 gene, has a greater influence on the risk of developing prostate, pancreas and stomach cancers, as well as impacting on the survival and age of onset of these cancers." (PMID 26236408, 2015). "Also, multiple other studies have shown that BRCA2 mutation but not BRCA1 is correlated with gastric cancer." (PMID 25349615, 2014). "Although BRCA1/2 alterations are well-established predictive biomarkers for PARP inhibitor efficacy in several malignancies, their role in gastric cancer remains incompletely defined." (PMID 42022316, 2026). "The results highlight that epigenetic mechanisms, particularly methylation of RAD51, BRCA1, and BRCA2 genes, are frequently involved in gastric cancer development and progression." (PMID 40869030, 2025). "Through inducing the histone deacetylation of p21 promoter and inhibiting p21 transcription via CtBP and BRCA1, RBBP8 serves a vital regulator in gastric cancer." (PMID 37656243, 2023).
gastric cancer (continued). "It is also notable that UHRF1 regulates other TSG as observed with CDX2, CDKN2A, RUNX3, FOXO4, PPARG, BRCA1 and PLM in gastric cancer, SOCS3 and 3OST2 in endometrial carcinoma, RB1 in Jurkat and osteosarcoma cells, as well as BRCA1 in cancer breast cell lines." (PMID 29932172, 2018). "Further research, including sequencing of entire sequences of BRCA1 and BRCA2 genes, is necessary to ultimately determine their role of these two genes in gastric cancer in Poland." (PMID 26779294, 2016). "Thus, gastric cancers with signature 3 mutations bear other mutational hallmarks of failure of homology directed double-strand break repair, despite the absence of inactivating mutations in BRCA1 and BRCA2 genes." (PMID 26511885, 2015). "Gene expression levels of APTX, BRCA1 and ERCC1 were significantly lower in irinotecan-sensitive gastric cancer samples than those irinotecan-resistant samples (P < 0.001 for all genes), while ISG15 (P = 0.047) and Topo1 (P = 0.002) were significantly higher." (PMID 23517622, 2013). "As a supplement to the previous studies, the current study further demonstrated that higher APTX, BRCA1 and ERCC1 mRNA expression levels suggested lower likelihood of response to irinotecan-based chemotherapy in gastric cancer." (PMID 23517622, 2013). "We observed the significant interaction of BRCA1 and ERCC1 mRNA expression levels on sensitivity to cisplatin in total and gastric cancer patients." (PMID 18402708, 2008). "Our results demonstrate that ERCC1 and BRCA1 mRNA expression levels are correlated with in vitro chemosensitivity to cisplatin and/or docetaxel in malignant effusions of NSCLC and gastric cancer patients." (PMID 18402708, 2008). "We observed a clear correlation between ERCC1 and BRCA1 mRNA expression level and chemosensitivity to cisplatin, one of the most widely used agent in both NSCLC and gastric cancer." (PMID 18402708, 2008). "BRCA1, acts as a SUMO E3 ligase involved in DNA damage response in gastric cancer." (PMID 40821814, 2025). "Therefore, BRCA1 and RAD51 can be used as biomarkers for the clinical diagnosis of gastric cancer to evaluate the prognostic effect of the disease." (PMID 36035159, 2022). "In 318 patients with stage II/III sporadic gastric cancer cases, approximately half of the patients were identified as BRCA1 negative by IHC." (PMID 34707985, 2021). "It is also noteworthy that UHRF1 regulates a plethora of other TSGs among which RB1 especially in Jurkat and osteosarcoma cells, CDX2, CDKN2A, RUNX3, FOXO4, PPARG, BRCA1 and PLM, in gastric cancer, SOCS3 and 3OST2 in endometrial carcinoma as well as BRCA1 in cancer breast cell lines." (PMID 27839516, 2016). "Further, in gastric cancer, as EBV-induced hypermethylation targets and silences key tumor suppressor genes including APC, RASSF1, BRCA1, THBS1, and CDKN2A, DNA methyltransferase inhibitors may also serve as a new therapeutic treatment for patients with EBV-positive gastric cancer." (PMID 37234978, 2023). "In this study, we found that in the response of cisplatin to gastric cancer cells, selective inhibition of CDK1 could affect the function of BRCA1, while OXA could play an independent role, indicating that OXA could inhibit CDK1 and thus exert the function of inhibiting BRCA1." (PMID 34497808, 2021). "Our group, as a member of The Latin American Gastric Cancer Genetics Collaborative Group, recently described the role of germline mutations in homologous recombination pathway related genes such as PALB2, BRCA1, and RAD51C in patients with GC." (PMID 31600923, 2019).